MYCN (MYCN proto-oncogene, bHLH transcription factor)
Diseases named in the same sentence as MYCN in open-access papers (continued):
Sharing a sentence is not in itself a finding about the gene and the disease.
tumor (continued). "In MYCN-amplified tumor cells, glycolytic enzymes including hexokinase isoform 2 are upregulated, and enzymes associated with the TCA cycle and the electron transport chain, such as citrate synthase and isocitrate dehydrogenase isoform 2, are expressed at high levels." (PMID 32547946, 2020). "Combined with other clinical features, plasma MYCN/NAGK ratio could successfully distinguish heavier tumor burden, insufficient treatment, and poor prognosis." (PMID 32896084, 2020). "MYCN-amplified (MNA) tumours also show defective G1 checkpoint arrest." (PMID 32354033, 2020). "The results showed that knocking down HOXD-AS1 restrained MYCN expression in tumor xenograft, but silencing miR-520c-3p could partially rescue the suppressive function caused by HOXD-AS1 knockdown." (PMID 32857725, 2020). "Regarding MYCN protein levels, the results suggest that knocking down MYCNOS1 mainly affected MYCN-amplified tumor cells without the RB1 mutation." (PMID 33270844, 2020). "Since MYCN promotes the proliferation of cells and inhibits differentiation, the MYCN-amplified cells are often undifferentiated or poorly differentiated, which is consistent with the poor differentiation of the tumor cells in our clinical patients." (PMID 32569234, 2020). "Next, we undertook a clinical investigation of MYCN co-expression genes in human HCC tumor tissues." (PMID 31988297, 2020). "High plasma MYCN/NAGK ratio predicting MYCN amplification status of tumor." (PMID 32896084, 2020). "CYC065 induced significant tumor growth inhibition and increased overall survival in mice carrying MYCN-amplified Kelly NB tumor xenografts, but had weaker effects against non–MYCN-expressing SK-N-AS NB tumor xenografts, consistent with the modest effect on c-MYC levels." (PMID 33016930, 2020). "Although this may support the idea of tumor cells being addicted to MYC/MYCN signaling, such strategy should be taken with caution, as the authors showed increased resistance to apoptosis and ionizing radiation upon MYC suppression." (PMID 33585252, 2020). "Thus, hTERT-targeted oncolytic virotherapy appears to be a promising antitumor strategy for eliminating MYCN-amplified NB tumor cells via MYCN suppression." (PMID 32637577, 2020). "However, the contribution of MYCN to the recruitment of immune cells into the tumor and to the composition of the tumor immune microenvironment (TIME) has only begun to be explored." (PMID 33050533, 2020). "All these studies point to an active contribution of MYCN to tumor vascularization." (PMID 33050533, 2020). "Only two MYCN-amplified NB cells was used to determine the anti-tumor activity of ARV-825." (PMID 33324552, 2020). "Moreover, further in vivo ALKF1174L modelling showed drastic acceleration of MYCN-driven tumour formation in transgenic mice and zebrafish." (PMID 31937834, 2020). "Interrogation of a previous SNP array (Affymetrix Cytoscan 750K array) conducted on this patient sample for clinical care revealed that MYCN amplification and the major chromosomal losses (1p, 10q) and gains (1q, 2p, 13q and 17q), were all present in a tumour population that comprised 50% of cells." (PMID 31919402, 2020). "Instead, a combination of factors, including age at diagnosis, stage, tumor histology, tumor cell ploidy, and MYCN status, has been used to stratify patients into three pretreatment groups, low-, intermediate, and high-risk, according to The Children's Oncology Group (COG)." (PMID 32855766, 2020). "Dynamic MYCN gene expression is an integrated consequence of multiple signals in the tumor microenvironment, including tumor stemness/growth-promoting signals such as Wnt/β-catenin and IL-6-STAT3 signaling, lipid desaturation-mediated ER stress adaptation signals, and tumor suppressive miRNAs." (PMID 33937011, 2020).
tumor (continued). "Overall, these data indicate that the changes in the tumor formation are due to the direct effect of miR‐15a, miR‐15b, and miR‐16 on MYCN, and therefore could be considered tumor suppressors in NB." (PMID 31637848, 2020). "Thus, the inhibition of MYCN will be an important anti-tumor therapeutic strategy in many different human cancers with aberrantly over-expressed MYCN." (PMID 33628735, 2020). "Beyond the threshold of 6.965, the MYCN/NAGK ratio correlated with a heavier tumor burden." (PMID 32896084, 2020). "Together with other mutations causing RAS/MAPK pathway activation, ALK mutations are also enriched in relapsed cases and ALK activation was shown to accelerate MYCN-driven tumour formation through hitherto unknown ALK-driven target genes." (PMID 31937834, 2020). "MYCN bypasses any need to inactivate p107 or p130 for tumor development." (PMID 32824373, 2020). "In conclusion, plasma MYCN/NAGK ratio may be a promising indicator of MYCN amplification of tumor in NB." (PMID 32896084, 2020). "MYC could thus contribute to the creation of an immunosuppressive environment in a “hot” MYCN-NA tumor." (PMID 33050533, 2020). "NB patients were examined by fluorescence in situ hybridization (FISH) for MYCN amplification in the tumor mass or bone marrow samples to determine whether MYCN was amplified." (PMID 32569234, 2020). "Minor differences in response to treatments between the 2 orthotopic models used could potentially be attributed to MYCN amplification in NB1691 cells which led to in vivo tumours that formed more rapidly and were larger in size." (PMID 30536898, 2019). "COG A3961, a study conducted through COG utilized certain factors similar to the low risk study including age, MYCN status, INSS stage, INPC, and tumor cell ploidy to evaluate the ability to maintain excellent outcomes in patients with intermediate risk disease with reduced intensity chemotherapy." (PMID 30754710, 2019). "However, the tumor development in this mouse model is induced by Lin28B-mediated downregulation of Let-7 resulting in overexpression of MycN protein." (PMID 30760980, 2019). "FISH targeting the MYCN gene showed focal amplification in 18.5% of the tumor cells analyzed." (PMID 31365300, 2019). "Neuroblastoma patients are grouped as having low, intermediate and high-risk disease depending on different prognostic factors i.e. age at time of diagnosis, clinical stage, tumor histology and tumor differentiation, chromosome 11q status, MYCN amplification and DNA ploidy." (PMID 31852910, 2019). "Additionally, similar histopathology is observed between MYCN-amplified patient tumor samples and TH-MYCN tumors." (PMID 32903387, 2019). "Our previous analysis of protein and gene expression patterns in DIPG tumor tissue specimens revealed two molecular subgroups of DIPG with relative activation of either Sonic Hedgehog (SHh) or MYCN signaling, with TNC hypomethylation and increased expression in the SHh group." (PMID 31092287, 2019). "We observed that the majority of MYCN-amplified tumours (4 of 6) contained subclonal (<20% variant allele fraction) ALK aberrations while in MYCN-nonamplified tumours the majority of ALK mutations (8 of 10) were clonal." (PMID 30778092, 2019). "This raises the possibility that NB tumours with 2p gain may instead benefit from extra copies of MYCN and ALK wildtype receptor in collaboration with its recently described ligand, ALKAL2 located at 2p25." (PMID 30778092, 2019). "MYCN amplification occurred mainly in patients with high lactate dehydrogenase (LDH) and high neuron-specific enolase (NSE) levels (both P < 0.001), and MYCN-amplified patients had more events (tumor relapse, progression, or death) than MYCN-normal patients (P = 0.004)." (PMID 31685009, 2019). "Interestingly, MYCN inhibition resulted in reduced tumor growth and improved survival in a transgenic mouse model." (PMID 31620124, 2019). "Given that, MYCN suppresses DHA transporter or synthesis to favor tumor cell growth." (PMID 31856871, 2019).
tumor (continued). "The comparison of survival of patients with ALK wild-type or ALK mutation, with or without MYCN amplification showed a poorer survival in patients whose tumours harbour MYCN amplification, with or without ALK mutation." (PMID 30778092, 2019). "Amplified copies of MYCN are considered the most important marker for the prediction of tumour relapse and progression in NB, but they were only detected in 20–30% of NB patients, indicating there might be other oncogenes in the development of NB." (PMID 31511046, 2019). "DCR2 hypermethylation was associated with tumour stage, independent of MYCN status, and patients with this alteration had a poorer 5 year EFS, which was particularly significant among patients without MNA." (PMID 31088252, 2019). "In particular, tissue-specific enhancers define highly tumor-specific MYCN target genes." (PMID 31819055, 2019). "Interestingly, the pathways melanogenesis and Wnt signaling were identified in the DEGs from both [EμMyc/Casp2−/− v EμMyc] and [Th-MYCN/Casp2−/− v Th-MYCN] tumor comparisons." (PMID 30670683, 2019). "Natural killer (NK)-cell-derived exosomes carrying the tumor suppressor miR-186 induced cytotoxicity when internalized by MYCN-amplified NB cell lines, through an inhibitory action on MYCN expression, Aurora Kinase A (AURKA), and transforming growth factor (TGF)-β-receptors 1–2." (PMID 31533332, 2019). "Moreover, VCF2CNA predicted two additional MYCN amplification events among the remaining tumor samples, indicating that VCF2CNA can identify clinically relevant CNAs that were undetected by traditional methods of CNA detection." (PMID 31316100, 2019). "EGF has been reported to induce MYCN expression and to favor tumor growth." (PMID 31013771, 2019). "We firstly analyzed the DEGs in the Th-MYCN/Casp2−/− versus Th-MYCN tumor comparison." (PMID 30670683, 2019). "Overexpression of C2GNT1 mRNA levels was also observed in NB1 MYCN-amplified patient tumor sample." (PMID 30344930, 2018). "Interestingly, higher ESC mRNA signature scores were also observed in other tumor(cell line)s with MYCN amplification 44,45." (PMID 30504901, 2018). "We were interested whether this was reflected in the correlation between DYRK gene mRNA expression and MYCN tumor amplification in human NB tumors." (PMID 29977157, 2018). "However, MYCN knockdown significantly inhibited tumour growth and promoted apoptosis in vivo and in vitro." (PMID 29673070, 2018). "Therefore, loss of TAp73 activity in MYCN-overexpressed tumors can be associated with increased HIF-1 activity and thereby the stimulation of angiogenesis in tumor cells." (PMID 29371588, 2018). "Therapy for high-stage disease that is often accompanied by tumor MYCN over-expression, is not sufficiently effective, and causes frequent severe late effects." (PMID 29977157, 2018). "Mutation load correlates with the age of onset of tumor formation, with absence of mutations in the most rapidly developing MYCN/ALKF1174L and Lin28b driven mouse tumors." (PMID 29492199, 2018). "JQ1 could still inhibit MYC or MYCN levels after 24 or 72 h in both genetically engineered GTML2 tumor cells and in MYC-amplified MB002 cells." (PMID 29511348, 2018). "During the 22‐day observation period, tumour growth was inhibited in mice treated with MYCN shRNA." (PMID 29673070, 2018). "For seven patients of the older age group, the MYCN status in relapse tumour material was analysed." (PMID 29755120, 2018).
tumor (continued). "In addition to its known immune-suppressive activities, our data have shown that DMF exhibited the anti-tumor activity in MYCN-overexpressing NBL cell lines and in mouse NBL xenografts." (PMID 29445162, 2018). "The results show that stratification of high risk patient based on the DG score can be used as a prognostic factor for patients’ survival and it gives better results than previously known predictors such as tumor stage, MYCN amplification, age and TERT expression." (PMID 30012197, 2018). "However, reports of a potential association between levels of ALK expression and prognostic factors such as age, tumour stage, MYCN status and DNA ploidy are conflicting and variable in methodology." (PMID 29642598, 2018). "Moreover, MYCN knockdown was shown to significantly inhibit cell proliferation and tumour growth in vitro and in vivo." (PMID 29673070, 2018). "MYCN interacts with various promoter regions of both genes and non-coding RNA sequences, and as a result of this, modifies their transcriptional activation, thus promoting tumour growth." (PMID 29315268, 2018). "However, risk severity increases and survival rates decrease significantly depending on tumor characteristics which indicate amplification of MYCN, an oncogene shown to be correlated with poor prognosis." (PMID 29751783, 2018). "Moreover, ML327 blocked MYCN mRNA levels and tumor progression in established MYCN-amplified xenografts." (PMID 29207623, 2017). "Using a two-step real-time reverse transcription (RT)-PCR procedure, they found that the virus selectively replicated and significantly downregulated the MYCN expression and that it was capable of effectively silencing the MYCN gene and inducing apoptosis in the tumor cells." (PMID 29164063, 2017). "Our results for this 10-patient pilot cohort utilizing only archived tumor and blood plasma samples demonstrate that ddPCR analysis of either tumor gDNA or plasma-derived cfDNA accurately distinguished between MYCN-amplified and normal diploid status determined by FISH." (PMID 29156716, 2017). "Furthermore, the elevated expression of ASCL1 and LMO4 seen in the MYCN-overexpressing SY5Y-MYCN cells matched the high expression of these genes in the poor outcome tumours." (PMID 28187790, 2017). "Also, ALK inhibition has been shown to decrease the biological effects of MYCN amplified cells/tumor growth in xenograft models." (PMID 29018329, 2017). "Tumor specimens COA/UAB-3, /UAB-6, and /UAB-8 were obtained from patients older than 18 months, and had high-risk characteristics that included unfavorable histology and MYCN amplification." (PMID 29259192, 2017). "Of note, re-transplantation of cells from tumor #2 containing mycN and Survivin transgenes and from tumor #19 containing the mycN transgene alone showed dramatically shortened tumor latency when compared to tumors produced by freshly transduced U251-MGmycN/Survivin and U251-MGmycN/C cells." (PMID 29282022, 2017). "In cured animals only smaller remnants of differentiated tumor cells could be found, even after several months of MYCN reactivation." (PMID 28333115, 2017). "Furthermore, our in vivo experiment demonstrated that the combination of JQ1 and ABT-263 leads to marked tumor regression in MYCN-amplfied SCLC xenografts." (PMID 29156797, 2017). "These phenomena imply that NB tumor cells with partial genomic aberrance and MYCN amplification might have increased metastatic potential." (PMID 28915622, 2017). "These four cases illustrate the heterogeneity of NB tumors, and suggest that the tumor cells with partial genomic aberrance and MYCN amplification might have greater potential for metastasis." (PMID 28915622, 2017).
tumor (continued). "This overlap suggests the existence of common underlying mechanisms for HR-NB tumours that occur irrespective of MYCN copy number." (PMID 28246384, 2017). "Recent studies have shown that there are cases of unilateral Retinoblastoma that are devoid of Rb mutations and these tumors have distinct histological and genomic landscapes (e.g. high MYCN expression) that facilitate aggressive tumor formation similar to that seen in RB1(−/−) tumors." (PMID 29162051, 2017). "Taken together, our findings suggest that the axon guidance and Wnt signaling pathways might have a synergistic role in NB tumorigenesis and tumor progression, especially in MYCN-amplified NBs." (PMID 28915622, 2017). "MYCN copy numbers detected using plasma-derived cfDNA significantly correlated (Spearman’s correlation coefficient r = 0.8182) with the copy numbers measured in tumor gDNA." (PMID 29156716, 2017). "High expression and maintenance of alt-NHEJ ligases coupled with MYCN overexpression in differentiating NCSC and in resultant tumor tissues suggests the hypothesis that alt-NHEJ components mediate MYCN oncogenic activity." (PMID 29238067, 2017). "Importantly, TH-MYCN mice treated with MYCN anti-sense RNA show reduced tumor incidence and tumor mass." (PMID 28358317, 2017). "The R2* values acquired in Th-MYCN and Th-ALKF1174L/Th-MYCN were ∼43% lower than those determined at 7T in this study, are consistent with previously published values, and with those reported from human tumours at 3T." (PMID 28787429, 2017). "This might explain the increased contact-uninhibited cell growth of mycN and Survivin-transduced U251-MG cells and decreased tumor latency when compared to U251-MG cells only transduced with mycN." (PMID 29282022, 2017). "With challenging heterogeneity within the tumor subpopulation, prognostic factors for survival include age at diagnosis, tumor grade, tumor site, histology, and amplification of the v-myc avian myelocytomatosis viral oncogene neuroblastoma derived homolog (MYCN) gene." (PMID 28035057, 2017). "Many researchers have targeted MYCN transcription in the development of anti-tumor therapies." (PMID 26771642, 2016). "In human, while large amount of studies on MycN have been conducted in human tumor cells, the role of MycN in human neural crest development is completely unknown largely due to the lack of appropriate cell model." (PMID 26815535, 2016). "On the other hand, vast majority of studies on MycN have been conducted in human tumor cells, thus, the role of MycN in normal human neural crest development is completely unknown." (PMID 26815535, 2016). "But what if only a fraction of the tumor cells is MYCN‐amplified?" (PMID 26910568, 2016). "Thus, targeted MYCN expression in hGFAP-expressing cells of transgenic mice results in tumor formation in pancreatic and pituitary tissue." (PMID 27769070, 2016). "In support of this, other studies reported upregulated β-catenin and β-catenin target genes in high-risk NB tumor tissue without MYCN amplification in comparison to high-risk MYCN-amplified tumor sections." (PMID 27323822, 2016). "We here provide evidence that tumor cell senescence might be a major contributor to the tumor-inhibiting effects observed upon low-dose metronomic TPT in MYCN-amplified tumors." (PMID 26657295, 2016). "Furthermore, in a mouse xenotransplant-model for MYCN-amplified NB metronomic TPT leads to senescence selectively in tumor cells, complete or partial remission, prolonged survival and a favorable SASP." (PMID 26657295, 2016). "Collectively, these data show that GSI-I blunted growth of orthotopic MYCN non-amplified NB cell tumors, associated with decreased proliferation, evidence of mitotic catastrophe and inhibition of tumor angiogenesis." (PMID 27588497, 2016).